POLK (DNA polymerase kappa)
Description:
DNA polymerase specifically involved in DNA repair. Plays an important role in translesion synthesis, where the normal high-fidelity DNA polymerases cannot proceed and DNA synthesis stalls. Depending on the context, it inserts the correct base, but causes frequent base transitions, transversions and frameshifts. Lacks 3'-5' proofreading exonuclease activity. Forms a Schiff base with 5'-deoxyribose phosphate at abasic sites, but does not have lyase activity.
Synonyms: DINP; DINB1; POLQ
Tractability: Small molecule: a structure with a bound ligand is known. PROTAC: ubiquitination databases record sites on it; a small molecule that binds it is known.
Target class: Enzyme
Gene: Protein-coding gene on chromosome 5 (75,511,782 to 75,609,991, forward strand). Ensembl gene ENSG00000122008.
Subcellular location: Nucleus
Subcellular location (Human Protein Atlas): Nucleoplasm
Pathways (Reactome):
DNA Repair: Dual Incision in GG-NER; Dual incision in TC-NER; Gap-filling DNA repair synthesis and ligation in GG-NER; Gap-filling DNA repair synthesis and ligation in TC-NER; HDR through Homologous Recombination (HRR); Termination of translesion DNA synthesis; Translesion synthesis by POLK
Gene Ontology:
Molecular function: DNA polymerase activity; DNA-directed DNA polymerase activity; protein binding; damaged DNA binding; DNA binding
Biological process: cellular response to UV; DNA biosynthetic process; DNA damage response; DNA repair; error-prone translesion synthesis; nucleotide-excision repair, DNA gap filling; translesion synthesis
Cellular component: nucleoplasm; nucleus; site of DNA damage
Genetic constraint (gnomAD): Loss-of-function variants: 28 observed, 41.55 expected, observed/expected ratio (o/e) 0.67, 90% interval 0.5 to 0.92. The upper end of that interval is the gene's LOEUF score, 0.92, which puts it in group 3 of 6, group 1 being the genes least tolerant of losing a copy. Missense variants: 433 observed, 490.88 expected, observed/expected ratio (o/e) 0.88, 90% interval 0.81 to 0.95. Synonymous variants: 158 observed, 169.47 expected, observed/expected ratio (o/e) 0.93, 90% interval 0.82 to 1.06.
Homologues: Orthologues: chimpanzee POLK (98% identical), macaque POLK (95% identical), dog POLK (84% identical), mouse Polk (76% identical), pig POLK (76% identical), rat Polk (73% identical), tropical clawed frog polk (54% identical), guinea pig POLK (52% identical), zebrafish polk (49% identical), Caenorhabditis elegans polk-1 (29% identical), Drosophila melanogaster eco (17% identical). Paralogues in human: REV1 (20% identical), POLI (16% identical), POLH (16% identical), ESCO1 (7% identical), ESCO2 (7% identical).
Diseases named in the same sentence as POLK in open-access papers:
POLK is named in the same sentence as 39 diseases in open-access papers, as found by Europe PMC text mining. Sharing a sentence is not in itself a finding about the gene and the disease. The quoted sentences say what the papers report.
breast carcinoma (8 papers, 2016 to 2025). "Only two genes (MMS19 and POLK) are involved in DNA repair pathway, considered as the traditional pathway in which breast cancer genes are involved." (PMID 29879995, 2018). "Eight of these genes (except WNT2, GADD45B, FZD2, WNT7B, POLK, and PIK3R3) have been extensively studied in breast cancer." (PMID 32818022, 2020). "Enriched biological process and protein–protein interaction networks resulted in the identification of four novel breast cancer candidate genes namely MMS19, DNAH3, POLK and KATB6." (PMID 29879995, 2018). "In summary, these WES studies results and the functional annotation performed in the present study, altogether showed that MMS19, DNHA3, POLK and KATB6 are interesting breast cancer candidate genes." (PMID 29879995, 2018).
lung carcinoma (4 papers, 2017 to 2023). "POLK is associated with cancer cell proliferation and participates in platinum-chemotherapy tolerance in lung cancer." (PMID 36803971, 2023). "miR-939 regulates a large number of genes, such as WNT1, NTSR1, POLK, WWOX and SPN, that are related to lung cancer." (PMID 29228624, 2017).
glioma (3 papers, 2019 to 2024). A benign or malignant brain and spinal cord tumor that arises from glial cells (astrocytes, oligodendrocytes, ependymal cells). "To evaluate the association of two common POLK variants (rs3213801 C>T and rs5744533 C>T) with glioma, we conducted a case‐control study and genotyped these two POLK variants in 605 patients and 1300 healthy controls." (PMID 31595696, 2019). "Similar results were obtained in glioma patients with POLK rs5744533 polymorphism (OS: P = .37; PFS: P = .24)." (PMID 31595696, 2019). "Further studies on POLK polymorphisms and multi‐central studies are expected to provide more insights into the relationships between POLK SNPs and glioma risk." (PMID 31595696, 2019). "Therefore, we genotyped two cancer‐risk related SNPs of POLK (rs3213801 C>T and rs5744533 C>T) in 650 glioma patients and 1300 controls to explore their associations with glioma risk." (PMID 31595696, 2019). "Herein, the two POLK SNPs could be associated with older patients or patients who have lower glioma grade." (PMID 31595696, 2019). "Additionally, compared to patients harboring the CC genotype, the CT and CT+TT genotypes of POLK rs5744533 were increased in the patients with lower WHO grade glioma, indicating that POLK polymorphisms might exert protective functions in the development of glioma." (PMID 31595696, 2019). "We explored the relations between POLK SNPs and clinical parameters in glioma cases, such as age, gender, and WHO grade." (PMID 31595696, 2019). "However, the POLK rs3213801 CT genotype was found to be higher in older glioma patients (≥40) than in younger patients (P = .026)." (PMID 31595696, 2019). "Meanwhile, compared with patients harboring the CC genotype, the CT and CT+TT genotypes of POLK rs5744533 were increased in the patients with lower WHO grade glioma (CT vs CC: OR = 0.67, 95%CI: 0.47‐0.96, P = .028; CT+TT vs CC: OR = 0.71, 95% CI:0.51‐0.99, P = .044)." (PMID 31595696, 2019). "However, although our findings did not support the correlations between POLK polymorphisms and glioma in Han Chinese population, the possibility that the POLK polymorphisms confer genetic susceptibility to glioma in other populations cannot be excluded." (PMID 31595696, 2019). "Analysis of TCGA data revealed that low-grade glioma patients with high-level expression of RAD18 and POLK showed reduced survival probability when compared with RAD18-low and POLK-low groups respectively." (PMID 38438348, 2024). "Compared with patients harboring the CC genotype, the frequencies of POLK rs5744533 CT and CT+TT genotypes were increased in patients with lower World Health Organization (WHO) grade glioma (P = .028, 0.044, respectively)." (PMID 31595696, 2019). "Despite the negative results, further studies that investigate POLK SNPs in glioma would be worthwhile." (PMID 31595696, 2019).
basal cell carcinoma (1 paper, 2021). A carcinoma involving the basal cells. "Interestingly, numerous gene members in the basal cell carcinoma pathway were found to be regulated by multiple miRNAs, with the exception of POLK and KIF7; meanwhile, for many KmiRNAs, one of them (e.g., hsa-miR-320b, hsa-miR-18a-3p, and hsa-miR-370-3p) targets more than one gene members." (PMID 34395634, 2021).
cervical cancer (1 paper, 2022). A primary or metastatic malignant neoplasm involving the cervix. "To determine if the same was true for TLS genes other than the TLS polymerases (POLH, POLI, POLK, REV1, and REV3L), we segregated the cervical cancers in the TCGA database based on whether they did or did not have increased expression of at least one TLS gene." (PMID 36266721, 2022).
chronic hepatitis B (1 paper, 2016). "POLK is thus a potential therapeutic target for treatment of chronic hepatitis B." (PMID 27783675, 2016). "Our findings thus suggest that POLK is a key host factor required for cccDNA formation during a de novo HBV infection, and therefore, a potential target for therapeutic intervention of chronic hepatitis B." (PMID 27783675, 2016).
colon adenocarcinoma (1 paper, 2022). "We reanalyzed RNAseq data obtained from 452 patients with colon adenocarcinoma that we separated into two groups of 226 patients, each with low and high POLK gene expression in the corresponding tumors using the median as a cutoff value." (PMID 35800380, 2022).
colon cancer (1 paper, 2022). "Defining the precise involvement of POLK gene induction in the effect of RIP140 on the maintenance of genome integrity in colon cancer cells (in particular on the stability of microsatellites) and on their resistance to anticancer drugs will obviously require further work." (PMID 35800380, 2022).
cutaneous melanoma (1 paper, 2023). A primary melanoma arising from atypical melanocytes in the skin. "We extracted the cutaneous melanoma samples from The Cancer Genome Atlas (TCGA) and segregated the samples based on the mRNA expression of POLK." (PMID 37697436, 2023).
gastric cancer (1 paper, 2022). A primary or metastatic malignant neoplasm involving the stomach. "RNA sequencing–derived gene expression data was available for many of the gastric cancer samples, and showed significantly lower POLK expression in samples with a Sig.POLKΔ component in their SBS spectrum." (PMID 35017534, 2022).
lymphoma (1 paper, 2022). A malignant (clonal) proliferation of B- lymphocytes or T- lymphocytes which involves the lymph nodes, bone marrow and/or extranodal sites. "In vivo, cisplatin treatment significantly delayed the outgrowth of POLK-deficient lymphomas, and substantially increased the overall survival time of tumor bearing mice." (PMID 35819193, 2022). "Interestingly, we identify TLS polymerase Kappa (POLK) to be essential for tolerance of cisplatin lesions in a murine lymphoma model." (PMID 35819193, 2022). "Retroviral reconstitution of Polk desensitized the Polk-KO lymphoma, indicating that its hypersensitivity was solely dictated by the lack of POLK." (PMID 35819193, 2022).
malaria (1 paper, 2025). Malaria is a serious and sometimes fatal disease caused by a parasite that commonly infects a certain type of mosquito which feeds on humans. "Further studies identified a gene in malaria parasites encoding a PolK enzyme, whose inhibition makes P. falciparum parasites more sensitive to fosmidomycin and unable to utilize prenols." (PMID 40502756, 2025). "Currently, we identified a gene in malaria parasites that encodes a CTP-dependent prenol kinase (PolK) genetically related to its homologous enzymes in plants and green algae." (PMID 40502756, 2025). "Furthermore, we also searched for a PolK inhibitor as a pharmacological strategy to improve fosmidomycin efficacy for malaria treatment." (PMID 40502756, 2025). "Importantly, while this study focused on fosmidomycin as a specific inhibitor of the MEP pathway in malaria parasites, other MEP-targeting drugs, such as ribosome inhibitors (e.g., clindamycin), may also benefit from PolK disruption." (PMID 40502756, 2025).
melanoma (1 paper, 2023). A malignant, usually aggressive tumor composed of atypical, neoplastic melanocytes. "Thereby, suggesting that expression of POLK could explain a fraction of mutations in human melanoma, and provide physiological relevance to the observations in cultured cells." (PMID 37697436, 2023). "While 83 melanoma samples did not have detectable expression of POLK mRNA by sequencing, FPKM based binning resulted in 207 patients with high levels of POLK and 175 patients had lower expression of POLK." (PMID 37697436, 2023).
ovarian carcinoma (1 paper, 2018). A malignant neoplasm originating from the surface ovarian epithelium. "Recently, POLK have been reported as a new ovarian cancer susceptibility gene." (PMID 29879995, 2018).
serous ovarian cancer (1 paper, 2021). "The ORs associated for high-grade serous ovarian cancer were 3.01 for PALB2 (95% CI 1.59 to 5.68; p=0.00068), 1.99 for POLK (95% CI 1.15 to 3.43; p=0.014) and 4.07 for SLX4 (95% CI 1.34 to 12.4; p=0.013)." (PMID 32546565, 2021).
cancer (19 papers, 2012 to 2025). A tumor composed of atypical neoplastic, often pleomorphic cells that invade other tissues. "Dysregulation of POLK can lead to genetic instability in human cells, which is associated with some cancers." (PMID 36281462, 2022). "Since both situations can confer a selective growth advantage during cancer cell evolution, this underlines the importance of tight regulation of POLK gene expression at the transcriptional level for the maintenance of genome integrity." (PMID 35800380, 2022). "In addition, many cancer-associated single-nucleotide polymorphisms have been reported in the POLK gene, some of which are associated with poor survival and altered chemotherapy response." (PMID 31374881, 2019). "Numerous cancer-associated SNP variants have been identified in the POLK gene, which could impact pol κ function in several different ways." (PMID 31374881, 2019). "However, in cancer cells, POLK depletion causes instability at the FRA7H CFS locus." (PMID 30347795, 2018). "We prepared EBV-transformed cell lines from the primary lymphocytes of 3 patients bearing candidate variants (henceforth referred to as the POLD1/POLH cell line, POLE cell line, and POLK cell line) and from several age-and gender-matched cancer-free controls." (PMID 37095444, 2023). "Across cancers, we found that heterozygous loss events in XPC (2/5 tumor types), POLK (4/5), LIG4 (5/5), ATM (3/5), and TP53BP1 (3/5) were common in MYBL2 High tumors." (PMID 36358918, 2022). "DNA polymerase kappa (POLK), one of the specialized Y family DNA polymerases, functions in translesion synthesis and is suggested to be related with cancers." (PMID 31595696, 2019). "In contrast to POLH, the POLK locus is highly deleted in cancers." (PMID 30347795, 2018). "Implications of PolK’s role in both genome maintenance and mutagenesis will be highly relevant in recurrent chromosomal rearrangements that arise from breakage within fragile hotspot regions throughout cancer genomes, as well as progression of preneoplastic lesions to genomicaly unstable cancers." (PMID 30422114, 2018). "Therefore, our discovery here establishing the role of RIP140 in POLK gene regulation not only may explain why POLK is abnormally expressed in cancer, notably in CRC, but can also clarify why cancers cells respond differentially to anticancer genotoxic drugs that target DNA replication forks." (PMID 35800380, 2022). "These include POLK, NIFK, SRGN, CAMP, CD109, and PLAC1 that are upregulated in several cancers resulting in metastasis and poor prognosis." (PMID 33110154, 2020).
tumor (10 papers, 2013 to 2024). "Among DNA repair genes, we detected evidence of positive selection in the tumor suppressor-encoding PALB2 and in four DNA polymerase-encoding genes (POLA1, POLD1, POLK, and POLM)." (PMID 37728212, 2023). "A statistically significant association of high expression of RIP140 with a decreased risk of death in CRC patients was observed when their tumor exhibited low POLK gene expression but not in tumors with high POLK gene expression." (PMID 35800380, 2022). "Transcriptional deregulation of POLK gene expression may therefore participate in intestinal tumorigenesis and account, at least in part, for the tumor suppressor role of RIP140 that we previously suggested." (PMID 35800380, 2022). "We also found a significant reduction in the levels of tumor promoter GPs at the end of 4th week during 4-week intermittent fasting (POLK, CD109, CAMP, NIFK, SRGN), and 1 week after 4-week intermittent fasting (CAMP, PLAC1) compared with the levels before 4-week intermittent fasting." (PMID 33110154, 2020). "qPCR results revealed that the mRNA quantities of POLH, POLK, POLQ and REV3L in XP-V tumor cells were lower than those of the controls; however, the expression of POLI was higher in the XP-V tumor cells in the absence of UV irradiation (P<0.05)." (PMID 24260050, 2013). "Specifically, expression of POLK, POLQ and REV3L increased in the tumor cells while that of POLH, POLK, POLQ and REV3L decreased in the normal controls." (PMID 24260050, 2013). "In the present study, low expression of POLH, POLK and REV3L was observed in the XP-V tumor cells." (PMID 24260050, 2013).
infection (3 papers, 2014 to 2022). The state of being infected such as from the introduction of a foreign agent such as serum, vaccine, antigenic substance or organism. "Among them, several genes encoding for enzymes involved in DNA metabolism were induced upon infection, such as DNA polymerases POLK and POLB, DNA helicase RECQL, and DNA glycosylase SMUG1 involved in various types of DNA repair, including mismatch repair, base excision repair, and direct repair." (PMID 24812617, 2014).
POLK also shares sentences with these, for which no sentence is quoted: prostate carcinoma (2 papers); adenocarcinoma (1); colitis (1); colonic dysplasia (1); colorectal cancer (1); dysplasia (1); endometrial cancer (1); esophagus tumors (1); familial breast cancer (1); glioblastoma (1); infertile (1); leukemia (1); liver cancer (1); metabolic syndrome (1); neurological diseases (1); non-small cell lung carcinoma (1); pulmonary tuberculosis (1); Thyroid Carcinoma (1); uterine corpus endometrial carcinoma (1); viral infection (1); Werner syndrome (1).